TIMP3 (TIMP metallopeptidase inhibitor 3)
Diseases named in the same sentence as TIMP3 in open-access papers (continued):
Sharing a sentence is not in itself a finding about the gene and the disease.
chronic kidney disease (2 papers, 2013 to 2023). Impairment of the renal function secondary to chronic kidney damage persisting for three or more months. "Moreover, TIMP3 is the only known physiological inhibitor of ADAM17, a metalloprotease responsible for shedding of several ligands, in particular HB-EGF and TGFα, which are involved in the pathogenesis of chronic kidney disease and glomerulonephritis." (PMID 23401241, 2013).
clear cell renal cell carcinoma (2 papers, 2021 to 2025). "We also observed that in renal clear cell carcinoma, by constructing a prognostic model of immune-related genes, screening for six immune-related genes including TIMP3, patients in the high-risk group model had a worse prognosis and the high-risk group was enriched in more immune-related pathways." (PMID 40357367, 2025).
cognitive deficits (2 papers, 2020 to 2022). "ELISA results revealed that plasma levels of TIMP-3 in 65 patients with AD were significantly lower than those in 115 healthy control subjects and 71 mild cognitive impairment (MCI) subjects." (PMID 35629249, 2022). "As little is known about the clinical significance of plasma levels of TIMP-3, we screened TIMP-3 levels in the plasma of subjects with mild cognitive impairment (MCI) as well as in AD patients and compared them with healthy controls." (PMID 35629249, 2022).
colorectal adenocarcinoma (2 papers, 1997 to 2025). The most common type of colorectal carcinoma. "In conclusion, our research highlights the significant differential expression of TIMP3, particularly in colorectal adenocarcinoma, where it emerges as an influential factor in prognosis and clinical traits." (PMID 41009435, 2025).
dementia (2 papers, 2019 to 2022). Loss of intellectual abilities interfering with an individual's social and occupational functions. "The use of cell culture models combined with the use of powerful new imaging techniques can therefore offer the prospect of elucidating TIMP-3 pathology that underlies irreversible sight loss and dementia." (PMID 31877820, 2019). "We first compared the levels of TIMP-3 in the plasma from 251 subjects with dementia, subjects with MCI, and healthy controls." (PMID 35629249, 2022). "Interestingly, the plasma concentrations of TIMP-3 were significantly lower in the dementia group (0.39 ± 0.05 ng/mL) compared with the control group (0.6 ± 0.06 ng/mL) in the Mann-Whitney U-test results (p = 0.029)." (PMID 35629249, 2022). "We first showed that the fluid levels of TIMP-3 were lower in AD dementia patients compared with in non-AD patients." (PMID 35629249, 2022).
diabetic cardiomyopathy (2 papers, 2010 to 2021). Diabetic cardiomyopathy is a disorder of the heart muscle in people with diabetes. "Akita mice developed cardiac diastolic dysfunction, however TIMP3 deficiency did not aggravate this diabetic cardiomyopathy, unveiling a key and organ-specific role for TIMP3 in DN." (PMID 34181080, 2021). "It suggests that MMP-9 and TIMP-3, -4 are largely involved in diabetic cardiomyopathy in Akita." (PMID 20828387, 2010).
fibrosarcoma (2 papers, 2010 to 2018). A malignant mesenchymal fibroblastic neoplasm affecting the soft tissue and bone. "mRNA expression of TIMPs in matrix embedded fibrosarcoma cells demonstrates that cell-density significantly increased TIMP3 and TIMP4 expression but did not impact TIMP1 or TIMP2." (PMID 30220965, 2018).
infarcts (2 papers, 2021 to 2023). "According to these observations, in our study, by analyzing the presence of cerebral lacunar infarcts detected by MRI, we demonstrate a positive and significant independent association between MMP-2, TIMP-1, TIMP-2, TIMP-3 and the presence of the lesions." (PMID 37959331, 2023).
infiltrating ductal carcinomas (2 papers, 2021 to 2023). "One study revealed that TIMP3, which is frequently hypermethylated in infiltrating ductal carcinomas, is associated with increased tumor grade and nodal metastasis, along with increased expression of ER, progesterone receptor (PR), and Her2." (PMID 38069080, 2023). "Interestingly, a relationship between TIMP3 hypermethylation, lymph nodes metastasis and high tumor grading in invasive breast ductal carcinoma has been speculated." (PMID 33653378, 2021).
intervertebral disc degeneration (2 papers, 2012 to 2013). "A dominant imbalance of MMP-3/TIMP-1 and TIMP-2 relative to ADAMTS-4 and ADAMTS-5/TIMP-3 signifies an advanced stage of intervertebral disc degeneration." (PMID 22394620, 2012). "A dominant imbalance of MMP-3/TIMP-1 and TIMP-2 relative to ADAMTS-4 and ADAMTS-5/TIMP-3 is a possible indication of an advanced, irreversible stage of intervertebral disc degeneration." (PMID 22394620, 2012). "Integrated with these reports, our findings show that a state of dominant MMP-3/TIMP-1 and TIMP-2 imbalance relative to ADAMTS-4 and ADAMTS-5/TIMP-3 imbalance may indicate an irreversible stage of intervertebral disc degeneration." (PMID 22394620, 2012).
joint disorders (2 papers, 2012 to 2020). "After surgically induced joint instability, TIMP3 overexpression proved to be less protective in cartilage destruction than [-1A]TIMP3 at late stages of OA." (PMID 32518385, 2020).
leukemia (2 papers, 2016 to 2019). A malignant (clonal) hematologic disorder, involving hematopoietic stem cells and characterized by the presence of primitive or atypical myeloid or lymphoid cells in the bone marrow and the blood. "LTNK cells become resistant to leukemia cell-induced NKCAs and this phenomenon is associated with an apparent anti-AML cell activity, in vivo, leading to AML cell growth inhibition in immunodeficient mice and, in vitro, TIMP3 over-expression in NK cells." (PMID 26655503, 2016).
lung diseases (2 papers, 2013 to 2016). "We report herein for the first time two unrelated families carrying heterozygous mutations in TIMP3 with an autosomal dominant syndromic form of SFD associated with pulmonary disease." (PMID 27601084, 2016). "Indeed, there are several experimental data that plead for the pathological role of TIMP3 mutations in the pulmonary disease." (PMID 27601084, 2016). "Another aspect of the role of TIMP3 in the pulmonary disease is its involvement in the resolution of inflammation following lung injury, by regulating the neutrophil influx in the injury site." (PMID 27601084, 2016).
lymphedema (2 papers, 2009 to 2012). Excess fluid collection in tissues, causing swelling. "Because lymphangiogenesis is a well described feature of filarial lymphedema, it is of interest to note the significantly deceased production of TIMP-3 as well as decreased levels of MMP/TIMP-2 ratios in filarial lymphedema." (PMID 22679524, 2012). "TIMP3 mutations cause Sorby's fundus dystrophy, a disease, where choroidal vessel integrity is affected; SOX18 inactivation leads to lymphedema-distichiasis syndrome, with clinical signs of edema and abnormal morphology of capillaries and arterioles and FLT4 mutations cause Nonne-Milroy lymphedema." (PMID 19924294, 2009).
medulloblastoma (2 papers, 2013). A malignant, invasive embryonal neoplasm arising from the cerebellum. "Furthermore, SPARC overexpression induced a decreased expression of MMP9 and an increase of TIMP3 in medulloblastoma tumor." (PMID 23935929, 2013).
myocardial disease (2 papers, 2020 to 2021). "So far, the causal roles of MT1-MMP and TIMP-3/4 in the progression of myocardial disease have been demonstrated." (PMID 34702968, 2021). "The causal role of TIMP3 in progression of myocardial disease has been extensively explored in animal models." (PMID 32612540, 2020).
non-alcoholic steatohepatitis (2 papers, 2019 to 2021). "Consequently, restoration of TIMP3 expression in mouse models of non-alcoholic steatohepatitis (NASH) reduced ADAM17 activity and lowered fibrotic activity in the liver, suggesting that ADAM17 is essential for NASH pathology." (PMID 31601007, 2019).
pancreatic adenocarcinoma (2 papers, 2014 to 2016). "However, the down-regulation of TIMP3 protein not resulting from TIMP3 promoter hypermethylation has also been reported in pancreatic adenocarcinoma; this phenomenon is also known to be associated with microRNA and the loss of heterozygosity." (PMID 27410681, 2016).
papillary thyroid carcinoma (2 papers, 2009 to 2022). "Recent research indicated that Angiopoietin-1 played a role in lymph node metastasis and invasiveness of papillary thyroid carcinoma TIMPs, which comprise a family of four protease inhibitors: TIMP1, TIMP2, TIMP3, and TIMP4." (PMID 36672532, 2022).
retinal disease (2 papers, 2024). "Including this study, 23 heterozygous variants in TIMP3 have been reported in patients presenting with retinal disease." (PMID 38612555, 2024). "Out of the 23 TIMP3 variants previously reported to be retinal disease-causing, c.499G>A p.(Asp167Asn) did not meet the ACMG/AMP criteria for pathogenic/likely pathogenic." (PMID 38612555, 2024).
sarcoma (2 papers, 2007 to 2019). A usually aggressive malignant neoplasm of the soft tissue or bone. "Whereas the TIMP1 and TIMP3 co-expressed gene profiles from cancers of various origins were more interspersed with less apparent grouping of any specific cancer type (carcinoma, sarcoma, hematologic)." (PMID 31882975, 2019).
serous ovarian cancer (2 papers, 2024 to 2025). "The target genes analyzed in this study (e.g., ITGB1, TIMP3, and BRAF) were selected based on their strong prognostic relevance identified from cBioPortal survival analyses of high-grade serous ovarian carcinoma." (PMID 41294900, 2025). "To elucidate the post-transcriptional mechanisms contributing to the differential expression of prognostic genes identified in Section 3.1, we next investigated microRNAs (miRNAs) that may regulate TIMP3, BRAF, and ITGB1 in high grade serous ovarian cancer (HGSOC)." (PMID 41294900, 2025).
skin cancer (2 papers, 2018 to 2022). "Our findings suggest significant modifications of the effect of the association between arsenic exposure and skin cancer risk by the TIMP3 rs9619311 and rs2234921 variants." (PMID 36499314, 2022). "Herein, we conducted a cohort follow-up study to investigate the effects of TIMP3 promoter polymorphisms on skin cancer risks in 1078 individuals from an arsenic-exposed population." (PMID 36499314, 2022). "In this study, we examined contributions of the TIMP3 -1296 T > C (rs9619311) and -915 A > G (rs2234921) SNPs to arsenic-induced skin cancer/lesion risk." (PMID 36499314, 2022). "We observed borderline associations between TIMP3 genotypes and skin cancer risk." (PMID 36499314, 2022). "In this study, we aimed to investigate effects of the TIMP3 -1296 T > C (rs9619311) and -915 A > G (rs2234921) single-nucleotide polymorphisms (SNPs) on skin cancer risk in an arsenic-exposed population, and to evaluate the influence of allele-specific changes by an in silico analysis." (PMID 36499314, 2022). "Although the TIMP3 genotype was a weak independent predictor of skin cancer risk, we examined whether the genotype and arsenic exposure had an interactive effect on the skin cancer risk." (PMID 36499314, 2022). "The predicted TFs and their differential binding affinities to the TIMP3 promoter provide insights into how TIMP3 interacts with arsenic through TFs in skin cancer formation." (PMID 36499314, 2022). "Based on this cohort study, our data suggest that TIMP3 -1296 T > C and -915 A > G promoter SNPs are not likely significant predictors of skin cancer/lesion risk among Taiwanese participants." (PMID 36499314, 2022). "But, the TIMP-3 methylation was not significantly changed in other cancer cell lines including the colon, liver and skin cancer cell lines." (PMID 29467412, 2018).
transitional cell carcinoma of the bladder (2 papers, 2015 to 2023). "Furthermore, the TIMP-3 mRNA expression and its correlation with clinical characters of urothelial bladder carcinoma was analyzed using The Cancer Genome Atlas database (TCGA)." (PMID 36860920, 2023). "Besides, the data from TCGA demonstrated that the TIMP-3 mRNA levels showed significant relationship to higher tumor stage, tumor T status and lymph node status in urothelial bladder carcinoma." (PMID 36860920, 2023). "Still, the TIMP-3 mRNA level between no metastasis and metastasis form of urothelial bladder carcinoma was nearly identical." (PMID 36860920, 2023).
viral infection (2 papers, 2022 to 2025). "TIMP3 plays a key role in cell adhesion and migration at the cellular level and correlates with the severity of virus infection." (PMID 35392111, 2022).
abdominal aortic aneurysm (1 paper, 2020). Enlargement and ballooning of the vessel that supplies arterial blood to the abdomen, pelvis and legs. "Timp3-deficiency suppressed the hypertensive response to Ang II, however induced abdominal aortic aneurysm (AAA) after 4 weeks of Ang II infusion, due to degradation of the elastin fibers and adverse remodeling of the aortic wall." (PMID 32612540, 2020).
actinic keratosis (1 paper, 2022). A precancerous lesion of the skin composed of atypical keratinocytes. "In addition, the results of quantitative real-time PCR and immunohistochemistry analysis demonstrated the abnormal expression of TIMP3 and ATG9A in actinic keratosis and cutaneous squamous cell carcinoma skin tissues." (PMID 35450405, 2022).
acute kidney injury (1 paper, 2025). Sudden and sustained deterioration of the kidney function characterized by decreased glomerular filtration rate, increased serum creatinine or oliguria. "In patients, serum levels of TIMP-1 and TIMP-3 have been found to increase during the process of acute kidney injury, which has been suggested as a possible non-invasive marker of acute kidney injury." (PMID 40649789, 2025).
age (1 paper, 2024). A temporal measurement of the time period elapsed since an identifiable point in the life cycle of an organism. "TIMP3 upregulation preserves ECM integrity, crucial for skin resilience and regeneration, while FN1 and ELN actions further enhance wound healing and elasticity, mitigating age-related skin degradation." (PMID 39684852, 2024).
amoebiasis (1 paper, 2025). "In-depth analysis of the top 50 interacting genes using LinkedOmics showed that TIMP3 was directly implicated in the ECM receptor interaction, focal adhesion, protein digestion and absorption, and amoebiasis pathways." (PMID 41009435, 2025).
amyloid (1 paper, 2022). "Considering that amyloid deposits are frequently observed in brain vessels in AD, TIMP-3 might be involved in amyloid deposits in brain vessels." (PMID 35629249, 2022).
Ascites (1 paper, 2021). Accumulation of fluid in the peritoneal cavity (between the layers of the peritoneum that lines the abdomen). "The expression of TIMP-1 was highest, followed by TIMP-2 and then TIMP-3 in CN ascites." (PMID 35047406, 2021).
benign meningioma (1 paper, 2014). A grade I, slowly growing meningioma. "Barski assessed TIMP3 hypermethylation with MS-PCR and direct sodium bisulfite sequencing and revealed TIMP3 methylation in 67% of anaplastic meningiomas but less in atypical (22%) or benign meningiomas (17%)." (PMID 24722350, 2014).
bone tumors (1 paper, 2022). "miR-21: significantly overexpressed in different tumor types, in particular in bone tumors, it is involved in the regulation of many tumor suppressor genes and apoptosis-related proteins including tropomyosin-1 (TPM1), programmed death protein 4 (PDCD4), and metalloproteinase inhibitor 3 (TIMP3)." (PMID 35216464, 2022).
cardiac anomalies (1 paper, 2023). "A reported association between autosomal TIMP3 variance and congenital cardiac anomalies was replicated." (PMID 37800145, 2023). "Common variants in TIMP3 in relation to congenital cardiac anomalies (CCA)." (PMID 37800145, 2023).
cardioembolic stroke (1 paper, 2022). "In addition, we also analysed the causal relationship between TIMP-3 and the main subtypes of IS (large artery stroke [LAS], small vessel stroke [SVS], cardioembolic stroke [CES]), and ICH (lobar intracerebral haemorrhage [LICH] and non-lobar intracerebral haemorrhage [NLICH])." (PMID 35444693, 2022).
cerebral edema (1 paper, 2018). "Although TIMP-3 appears to play an important role in cerebral edema after TBI, the association of TIMP-3 with ARDS after TBI has not been studied." (PMID 30023434, 2018).
cervical adenocarcinoma (1 paper, 2024). An adenocarcinoma arising from the cervical epithelium. "Studies have reported that TIMP3 was more frequently methylated in cervical adenocarcinoma than in SCC (53.3–63.0% vs. 5.0–8.1%)." (PMID 38542164, 2024). "Based on previous studies, TIMP3 methylation is a potential biomarker to distinguish cervical adenocarcinoma from SCC." (PMID 38542164, 2024).
chronic heart failure (1 paper, 2020). "By inhibiting metalloproteinase inhibitor 3 (TIMP3), miR-206 has also been shown to attenuate cardiac fibrosis in the setting of chronic heart failure." (PMID 32266222, 2020).
chronic obstructive pulmonary disease (1 paper, 2024). A chronic and progressive lung disorder characterized by the loss of elasticity of the bronchial tree and the air sacs, destruction of the air sacs wall, thickening of the bronchial wall, and mucous accumulation in the bronchial tree. "Pathogenic variants in TIMP3 have also been reported to possibly be associated with chronic obstructive pulmonary disease; in this study, however, all the mutation carriers denied having any bronchopulmonary problems." (PMID 38612555, 2024).
collagen diseases (1 paper, 2013). "Thus, the MMP-3 to MMP-1 ratio, and levels of TIMP-3, MMP-9, andosteopontin could be prognostic markers for AoDILD in collagen diseases." (PMID 23405989, 2013).
Crohn disease (1 paper, 2015). A gastrointestinal disorder characterized by chronic inflammation involving all layers of the intestinal wall, noncaseating granulomas affecting the intestinal wall and regional lymph nodes, and transmural fibrosis. "Crohn's disease endoscopic index of severity (CDEIS) value correlated positively with macrophage TIMP-1 and stromal TIMP-3 and negatively with epithelial TIMP-3 which also negatively correlated with C-reactive protein values (CRP)." (PMID 25948887, 2015).
cutaneous melanoma (1 paper, 2015). A primary melanoma arising from atypical melanocytes in the skin. "It was previously shown by our group that miR-21, a potential regulator of TIMP3, is over-expressed in cutaneous melanoma." (PMID 25587717, 2015).
dilatation (1 paper, 2017). "Previous studies described protective effects of TIMP-3 during atherogenesis and aortic dilatation in rabbits, as well as mice." (PMID 27756793, 2017).
diverticulitis (1 paper, 2024). An infection that develops in the diverticula of the intestinal tract. "Whilst a collagen deficit does not identify individuals who will go on to develop diverticulitis, one study demonstrated downregulation of MMP2, MMP9 and MMP13 expression and an increase in MMP1, TIMP1 and TIMP3 in inflamed mucosa of patients with diverticulitis versus Crohn’s disease." (PMID 38831715, 2024).
Endometrial Cyst (1 paper, 2018). It is caused by endometriosis, and formed when a tiny patch of endometrial tissue (the mucous membrane that makes up the inner layer of the uterine wall) bleeds, sloughs off, becomes transplanted, and grows and enlarges inside the ovaries. "With regard to mean TIMP3 concentrations we showed significantly lower values in the group of patients with endometrial cysts compared to patients with benign cysts, p = 0.01." (PMID 29304854, 2018).
ependymoma (1 paper, 2009). A WHO grade II, slow growing tumor of children and young adults, usually located intraventricularly. "The tumors suppressor genes RASSF1, CDKN2A, CDKN2B, p14ARF and TP73, as well as other genes potentially involved in the tumorigenesis of ependymomas, such as CASP1, MGMT, TIMP3 and THBS1 are epigenetically silenced by aberrant promoter methylation in subsets of ependymomas." (PMID 19333441, 2009).